KDM3A (lysine demethylase 3A)
Diseases named in the same sentence as KDM3A in open-access papers (continued):
Sharing a sentence is not in itself a finding about the gene and the disease.
cardiac hypertrophy (10 papers, 2018 to 2025). "In transgenic mice with postnatal myocyte-selective KDM3A overexpression exposed to transaortic constriction, a more severe cardiac hypertrophy was observed." (PMID 40076868, 2025). "KDM3A is a demethylase of H3K9me2 residues with a similar effect on the production of cardiac hypertrophy to that detected with KDM4A." (PMID 36523510, 2022). "KDM3A is also involved in cardiac hypertrophy as well as fibrosis and is a crucial upstream regulator of the PI3K/Akt signaling pathway." (PMID 36092165, 2022). "According to recent studies, increased KDM3A expression in myocardial cells has a positive association with ANP/BNP transcription and participates in pressure-induced myocardial hypertrophy by regulating H3K9me2 levels." (PMID 35571189, 2022). "As a type of H3K9me2 histone demethylase, KDM3A is proactively-involved in the crucial processes of cardiovascular hypertrophy and fibrosis." (PMID 36700466, 2022). "Consistent with the echocardiography results, KDM3A-KO obviously relieved myocardial hypertrophy and fibrosis compared with the WT rats after DM and DM + GC treatments." (PMID 35571189, 2022). "In this study, we reveal a previously unidentified role of KDM3A in promoting pathological ventricular remodeling, and corresponding anti-cardiac hypertrophy/remodeling efficacy of the KDM inhibitor JIB-04." (PMID 30531796, 2018). "KDM3A promoted pressure overload–induced cardiac hypertrophy and fibrosis." (PMID 32625104, 2020). "Similarly, cardiomyocyte conditional knockout of KDM3A in mice defies the development of pressure overload-induced cardiac hypertrophy; it is not clear whether KDM3A deletion in endothelial cells would recapitulate this phenotype." (PMID 32733885, 2020).
diabetes (10 papers, 2017 to 2025). "Interestingly, mouse mutants for the histone N-lysine demethylase Kdm3a (Jmjd1a, Tsga, or Jhdm2a) are obese, predisposed to diabetes, and have male infertility phenotypes overlapping with mouse models of dysfunctional cilia." (PMID 28246120, 2017). "For instance, KDM3A inhibition is considered a promising avenue for the restoration of vascular function in diabetes-mediated metabolic memory." (PMID 35338235, 2022). "The KDM3A inhibition could significantly ameliorate the adverse effect of hyperglycemia in both diabetes model and diabetic intensive glycemic control model." (PMID 35571189, 2022). "In an independent study, H3K9-specific demethylase JHDM2A (also known as KDM3A) was shown to be involved in regulating the expression of metabolic genes, indicating epigenetic regulation as key to diabetes-dependent microvascular complications." (PMID 34685528, 2021). "Similarly, H3K9-specific demethylase JHDM2A (also known as JHMJD1A and KDM3A) has also been shown to be involved in regulating the expression of metabolic genes, strengthening the role of epigenetic regulation of metabolic genes in microvascular complications of diabetes." (PMID 29085333, 2017).
hepatocellular carcinoma (10 papers, 2016 to 2025). A malignant tumor that arises from hepatocytes. "The compound inhibits the binding of ABCF1-K430 to the KDM3A promoter and suppresses hepatocellular carcinoma organoid growth." (PMID 40994548, 2025). "This binding upregulates KDM3A expression and promotes hepatocellular carcinoma (HCC) malignant progression through the transcriptional activation of the HIF signaling pathway." (PMID 41007358, 2025). "ABCF1 K430la mediates its nuclear translocation, upregulates KDM3A expression, and enhances H3K9me2 demethylation, activating the HIF1A pathway to promote hepatocellular carcinoma progression." (PMID 40994548, 2025). "Interestingly, this work showed that the silencing of KDM3A decreased phosphatidylinositol 3-kinase (PI3K) pathway activity which is a well-known oncogenic pathway and is often activated in hepatocellular carcinoma to promote survival and proliferation." (PMID 36650321, 2023). "The level of KDM3A in hepatocellular carcinoma (HCC) is higher than that in normal tissues (n = 110)." (PMID 32354028, 2020).
Infertility (10 papers, 2010 to 2021). "As KDM3A is likely important for human fertility, introduction of any mutation in this gene could lead to infertility." (PMID 30053768, 2019). "Consequently, the existence of any mutation in KDM3A gene investigated in infertile men (azoospermia and oligozoospermia with more than 90% head abnormality) using PCR-SSCP." (PMID 30053768, 2019). "It has been reported that KDM3A is important in spermatogenesis and male KDM3A knockout mice are infertile." (PMID 34220955, 2021). "Contrarily, a targeted disruption of JHDM2A, a specific H3K9me2/1 demethylase-also known as KDM3A-results in a complete loss of TNP1 and PRM1 expression, defective chromatin condensation and infertility." (PMID 32121034, 2020). "In this study, it was found that hsa-miR-27a-3p overexpress in NOA men than OA men and this miRNA can potentially match with the 3'UTR of KDM3A transcript and prevent its translation and lead to infertility in NOA men." (PMID 33349804, 2020). "In this work, for the first time, the existence of KDM3A gene mutation was investigated in non-cancerous testis tissue of human infertile men to reveal any relationship between this gene and infertility." (PMID 30053768, 2019). "Although KDM3A is found to be mutated in infertile males, its role in infertility is not clear." (PMID 33477877, 2021). "Thus, there is uncertainty over the role of KDM3A gene in the incidence of infertility in humans." (PMID 30053768, 2019). "Without the function of KDM3A in round spermatids, excessive methylation would lead to the transcription suppression of TNP1/PRM1 genes and the occurrence of infertility in animal models." (PMID 33349804, 2020).
pancreatic cancer (8 papers, 2020 to 2023). "Overexpressed KDM3A in pancreatic cancer cell line HPNE formed foci and spheres in culture and formed tumours and metastases in mice." (PMID 36008383, 2022). "Alternatively, pancreatic cancer cells, through the KDM3A-mediated overexpression of EGFR decrease T-cell infiltration." (PMID 33671588, 2021). "KDM3A knockdown in pancreatic cancer cells considerably reduces colony formation, spheroid formation, migration, and invasion compared with the findings in control cells." (PMID 32354028, 2020). "KDM3A is increased under hypoxia through pancosphere formation in pancreatic cancer cells, thereby increasing the DCLK1 mRNA level." (PMID 32354028, 2020). "KDM3A level can be elevated by hypoxia in pancreatic cancer and the incremental expression of KDM3A could stimulate cancer development whereas its suppression had the opposite effects." (PMID 34044859, 2021). "Particularly, KDM3A has been reported to enhance the expression of DCLK1 with the removal of di‐ and mono‐methyl residues from H3K9me2/me1, and their high expression in pancreatic cancer tissues was correlated with shorter survival times of patients." (PMID 33350586, 2021). "Both KDM3A and DCLK1 mRNA levels are higher in human pancreatic tumor tissues than in non-tumor pancreatic tissues, and their expression is correlated with shorter survival times of patients with pancreatic cancer." (PMID 32354028, 2020). "KDM3A is overexpressed in pancreatic tumor cell lines and tissues compared with that in adjacent non-tumor tissues such as islet and acinar cells." (PMID 32354028, 2020).
neuroblastoma (7 papers, 2014 to 2020). Neuroblastoma (NB) is the most common solid, extracranial childhood tumor. "KDM3A has also been implicated in neuroblastoma metastasis and the HDM enzyme KDM4C has been shown to be a regulator of BCa lung metastasis and an activator of LOXL2 expression." (PMID 25488809, 2015). "KDM3A is upregulated in neuroblastoma, which is the most common pediatric extracranial tumor originating from precursor neuroblast cells." (PMID 32354028, 2020). "As a result, N-myc induces neuroblastoma cell migration and invasion by modulating KDM3A and MALAT1 levels, providing the evidence for the development of a KDM3A-selective inhibitor to block neuroblastoma metastasis." (PMID 32354028, 2020). "Additionally, KDM3A and MALAT1 promote the migration and invasion of neuroblastoma cells, whereas the small-molecule pan-KDM inhibitor dimethyl N-oxalylglycine (DMOG) (2-OG cofactor inhibitor) inhibits such effects." (PMID 32354028, 2020).
Azoospermia (6 papers, 2016 to 2025). Absence of any measurable level of sperm,whereby spermatozoa cannot be observed even after centrifugation of the semen pellet. "Regarding the important roles of miRNAs in control of gene expression, this study investigates the effect of hsa-miR-27a-3p on KDM3A transcription and the ability of this miRNA as a diagnostic biomarker for azoospermia men." (PMID 33349804, 2020). "MiR-30a-5p is overexpressed in non-obstructive azoospermia (NOA) patients compared to obstructive azoospermia (OA), and miR-30a-5p could potentially target the KDM3A transcript and hinder it from being translated." (PMID 37056229, 2023). "Additionally, the expression shrinkage of KDM3A is significantly correlated with human azoospermia phenotype." (PMID 33349804, 2020). "The results of that research showed that the expression of all the studied genes including KDM3A, TNP1, and PRM1 in all histological groups of azoospermia men with the tissue pattern of SCOC suggested a significant difference in the expression of hypospermatogenesis." (PMID 33349804, 2020). "The expression ratio of histone demethylase KDM3A to protamine-1 mRNA has been proposed as a reliable marker for successful TESE in men with both obstructive and non-obstructive azoospermia." (PMID 40901096, 2025).
gastric cancer (6 papers, 2016 to 2025). A primary or metastatic malignant neoplasm involving the stomach. "For example, low KDM3A expression is also associated with an aggressive phenotype and poor prognosis in gastric cancer." (PMID 38165573, 2024). "The expression of IFN response genes negatively correlated with KDM3A expression in gastric cancer patients, and KDM3A knockout elevated the expression of CXCL10, ISG15 or IFNβ." (PMID 40940894, 2025). "In conclusion, this study support KDM3A as a key epigenetic regulator influencing the tumor microenvironment and immunotherapy response in gastric cancer." (PMID 39031630, 2024). "Overall, this study highlights the potential of KDM3A as a promising therapeutic target for enhancing immunotherapy efficacy in gastric cancer." (PMID 39031630, 2024). "Our in vitro experiments revealed that inhibiting KDM3A suppressed gastric cancer cell proliferation, as measured by CCK8 cell viability." (PMID 39031630, 2024). "We further confirmed the overexpression of KDM3A in gastric cancer tissues compared to normal and adjacent tissues using Guangdong Province People's Hospital clinical samples." (PMID 39031630, 2024). "Remarkably, we found that the specific depletion of KDM3A led to a substantial increase in H3K4me2 levels, particularly in gastric cancer cells." (PMID 39031630, 2024). "primarily knocked down KDM3A to explore its function in gastric cancer, whereas our study involved knocking out KDM3A, leading to a more comprehensive understanding of its role." (PMID 39031630, 2024). "We collected 40 clinical samples from gastric cancer patients at Guangdong Province People's Hospital and conducted immunohistochemistry (IHC) to assess KDM3A expression." (PMID 39031630, 2024). "Furthermore, our bioinformatics analysis revealed that tumor‐intrinsic IFN plays a pivotal role in reversing the non‐MSI TME and is regulated by KDM3A in gastric cancer." (PMID 39031630, 2024). "Our analysis revealed that KDM3A was significantly and highly expressed in gastric cancer." (PMID 39031630, 2024). "Next, we explored the clinical significance of KDM3A expression in gastric cancer." (PMID 39031630, 2024). "Notably, KDM3A ablation increased in H3K4me2 levels, specifically in gastric cancer." (PMID 39031630, 2024). "In this study, we identified KDM3A as a key regulator of the non‐MSI TME and immunotherapy sensitivity in gastric cancer." (PMID 39031630, 2024). "In conclusions, this study highlights KDM3A as a potential target for TME remodeling and the enhancement of antitumor immunity in gastric cancer through the regulation of the ERV‐MAVS‐IFN axis." (PMID 39031630, 2024). "Consistent with previous research, we observed a significant increase in the infiltration of CD4 T cells, CD8 T cells, and NK cells in KDM3A‐ablated tumors, suggesting that targeting KDM3A could be a promising strategy for reversing the non‐MSI TME in gastric cancer." (PMID 39031630, 2024). "Furthermore, we observed a negative correlation between KDM3A expression and tumor‐intrinsic IFN signaling or immunotherapy response in gastric cancer patients." (PMID 39031630, 2024).
Hyperglycemia (6 papers, 2020 to 2025). An increased concentration of glucose in the blood. "Therefore, KDM3A knock-out alleviates long-term myocardial dysfunction and hypertrophy as well as mitigates fibrosis caused by hyperglycemia in the diabetic myocardium." (PMID 35571189, 2022). "Besides, by utilizing gain- and loss-of-functional approaches, we identified KDM3A as a novel regulator that accelerates hyperglycemia-mediated myocardial injury by promoting ROS generation, aggregating inflammatory reaction, and facilitating cell apoptosis in vitro and in vivo." (PMID 35571189, 2022). "In hyperglycemia-mediated myocardial injury, it was reported that KDM3A acts through the NFκB pathway, leading to excessive oxidative stress, apoptosis, inflammation and subsequent myocardial injury." (PMID 40076868, 2025). "In this study, we found that hyperglycemia induces continuous ROS generation, inflammatory responses, and apoptosis, accompanied by the over-expression of KDM3A and down-regulation of H3K9me2 even after glucose levels were normalized." (PMID 35571189, 2022). "In accordance with the ROS results, the TUNEL staining and IL-6/TNF-α results also showed that KDM3A knock-out evidently alleviated sustained apoptosis and inflammatory responses induced by hyperglycemia." (PMID 35571189, 2022). "Mechanistically, we demonstrated that KDM3A mediates hyperglycemia-induced injury in the diabetic myocardium mainly through enhancing the expression and transcriptional activity of NF-κB/P65." (PMID 35571189, 2022). "After considering these results, we concluded that KDM3A facilitates the expression and transcriptional activity of NF-κB/P65, thus leading to persistent myocardial injury in the context of hyperglycemia." (PMID 35571189, 2022). "KDM3A-NF-κB/P65 signaling pathway is expected to be a new therapeutic target for relieving hyperglycemia-induced persistent myocardial injury and cardiac dysfunction." (PMID 35571189, 2022). "This study was designed to determine whether KDM3A was involved in modulating hyperglycemia-induced continuous myocardial injury as well as to explore the underlying molecular biological mechanisms." (PMID 35571189, 2022). "In the light of these considerations, we speculated that KDM3A may also play a central role in the regulatory network of hyperglycemia-induced sustained myocardial damage." (PMID 35571189, 2022). "Mechanically, our data uncovered that KDM3A could promote the expression and transcriptional activity of nuclear factor kappa-B (NF-κB/P65), and the succedent rescue experiments further verified that KDM3A regulates hyperglycemia-induced myocardial injury in an NF-κB/P65 dependent manner." (PMID 35571189, 2022).
liver fibrosis (6 papers, 2016 to 2023). "KDM3A can be able to regulate the activation of hepatic stellate cells and liver fibrosis via epigenetic regulation of PPARγ." (PMID 32092824, 2020). "Moreover, studies have shown that KDM3A could regulate the activation of hepatic stellate cells and liver fibrosis through epigenetic regulation of PPARγ." (PMID 32092824, 2020). "We previously reported that the jumonji domain containing protein 1A (JMJD1A), also known as lysine demethylase 3A (KDM3A), modulates HSCs activation and liver fibrosis through demethylating H3K9me2 at PPARγ promoter and positively regulating its expression." (PMID 33391480, 2021). "One recent study has demonstrated that histone H3K9 demethylase JMJD1A (also called KDM3A) can act as a novel epigenetic regulator in modulating HSC activation and liver fibrosis by targeting PPARγ gene expression." (PMID 29954104, 2018).
Myocardial fibrosis (6 papers, 2018 to 2024). "Concretely, another study about myocardial infarction also has illustrated that KDM3A displays a low level, and KDM3A elevation can alleviate myocardial fibrosis, reduce inflammatory cytokine contents as well as decrease apoptosis cells." (PMID 35083842, 2022). "Consistently, we observed upregulation of Timp1 in cardiomyocytes of Kdm3a-Tg mice as well as myocardial fibrosis in response to TAC, with most of the fibrotic genes being upregulated in cardiac fibroblasts." (PMID 30531796, 2018). "Moreover, enforced KDM3A expression mitigated myocardial fibrosis, decreased the expression of the inflammatory cytokines as well as reduced the number of TUNEL‐positive cells and the levels of pro‐apoptotic proteins (P < .05)." (PMID 31755219, 2020). "In addition, KDM3A knockout aggravated myocardial fibrosis, cardiomyocyte apoptosis and the inflammatory response (P < .05)." (PMID 31755219, 2020). "In summary, we have established a novel role for KDM3A in LVH and demonstrated that KDM3A promotes LVH and myocardial fibrosis in response to pressure overload." (PMID 30531796, 2018). "KDM3A-activated TIMP1 in cardiomyocytes may be secreted into the ECM, subsequently activating resident cardiac fibroblasts and leading to myocardial fibrosis." (PMID 30531796, 2018).
myocardial infarction (6 papers, 2020 to 2022). Gross necrosis of the myocardium, as a result of interruption of the blood supply to the area, as in coronary thrombosis. "Our recently published study also indicated KDM3A take an active part in myocardial infarction-induced maladaptive remodeling by regulating inflammation and apoptosis." (PMID 35571189, 2022). "Additionally, prior studies have established that KDM3A depletion enhances inflammatory reactions, disrupts myocardial structure, and retards heart repair in myocardial infarction." (PMID 36700466, 2022). "Thus, it was previously demonstrated that KDM3A plays a major role in the up-regulation of Nox2 and Nox4 expression in experimental myocardial infarction." (PMID 36552592, 2022). "Compared with the wild‐type rat, knocking out the KDM3A gene augmented the area of myocardial infarction and led to further deterioration of cardiac function post‐MI when compared with those in the WT + MI group (P < .05)." (PMID 31755219, 2020).